ARID5A (AT-rich interaction domain 5A)
Diseases named in the same sentence as ARID5A in open-access papers (continued):
Sharing a sentence is not in itself a finding about the gene and the disease.
glioma (continued). "Based on datasets from the Chinese Glioma Genome Atlas (CGGA) and TCGA RNA sequencing, as well as clinical and molecular characterization, the expression of Arid5a was increased with higher glioma tumor grade." (PMID 35126382, 2021). "However, the expression pattern and biological role of ARID5A in glioma remains unknown." (PMID 34094918, 2021). "Also, high levels of Arid5a expression may regulate the immune response in glioma." (PMID 35126382, 2021). "Our findings show that ARID5A expression was upregulated in glioma compared with normal brain tissues by analyzing GEPIA and the expression of ARID5A in TCGA and the GTEx database." (PMID 34094918, 2021). "Our results demonstrate that the expression of ARID5A was upregulated in glioma compared with that in nontumor brain tissues." (PMID 34094918, 2021). "The analysis of glioma samples in the TCGA datasets revealed enrichment of apoptosis, cytokine-cytokine receptor interactions, JAK-STAT signaling, leukocyte transendothelial migration, and toll-like receptor signaling in the high Arid5a expression group." (PMID 35126382, 2021). "Our study on ARID5A was based on database mining, cell lines and animal experiments have not been conducted to confirm the role of ARID5A in glioma." (PMID 34094918, 2021). "Finally, we found that 1p/19q non-codeletion gliomas had a higher ARID5A expression level than 1p/19q co-deletion gliomas (P < 0.001)." (PMID 34094918, 2021). "In addition, Arid5a expression was higher in IDH-wild-type gliomas compared with IDH-mutant gliomas and in gliomas without 1p/19q co-deletion compared with 1p/19q co-deletion in gliomas." (PMID 35126382, 2021). "We found that the expression of ARID5A was significantly upregulated with increasing tumor grade and that high ARID5A expression was correlated with patient age, IDH wild-type gliomas, and 1p/19q non-codeletion gliomas." (PMID 34094918, 2021).
melanoma (3 papers, 2022 to 2024). A malignant, usually aggressive tumor composed of atypical, neoplastic melanocytes. "Compared with those in the low-risk group, the melanoma patients in the high-risk group had high expression of S100A11 and CPC3 and low expression of PSME2, ARID5A, and SERPINE2 and had a shorter survival time." (PMID 35646893, 2022). "In addition, PSME2 and other four gene markers for malignant cells (ARID5A, SERPINE2, GPC3, and S100A11) were combined to develop a prognostic signature in melanoma." (PMID 36583022, 2022).
Obesity (3 papers, 2019 to 2022). Accumulation of substantial excess body fat. "Consistently, Arid5a−/− mice showed reduced IL-6 production; mice with long-term loss of Arid5a developed adult-onset severe obesity." (PMID 36408139, 2022). "Il6-deficiency in mice resulted in higher adipogenesis and obesity, which result from insufficient Arid5a induction." (PMID 35126382, 2021). "Transcriptome data revealed that Arid5a binds to the promoter region of Pparγ, which is the leading cause of adipogenesis, and represses the transcription of the Pparγ gene, thereby inhibiting adipogenesis and obesity in mouse fibroblasts." (PMID 35126382, 2021). "Arid5a is induced by the cytokines IL-6 and IL-17, and because IL-6 is a strong inducer of Arid5a, it is likely that IL-6-deficient mice have insufficient activation of Arid5a, which results in unrestricted adipogenesis and obesity." (PMID 31867000, 2019). "In contrast, mice with forced expression of Arid5a are highly resistant to high-fat diet-induced obesity." (PMID 36408139, 2022). "For example, Arid5a binds to the promoter of Pparγ to suppress transcription, which leads to inhibition of adipogenesis and obesity and to lncRNA-AU021063 to augment invasion and metastasis in breast cancer." (PMID 35126382, 2021). "Following stimulation by IL6, Arid5a further represses Pparγ expression, which ameliorates adipogenesis and obesity." (PMID 35126382, 2021). "In addition, Arid5a controls adipogenesis and obesity in mice to maintain metabolic homeostasis." (PMID 35126382, 2021). "Therefore, by activating Arid5a, IL-6 is involved in the inhibition of adipogenesis and obesity." (PMID 31867000, 2019). "This increases the probability of Arid5a involvement in IL6 inhibition of adipogenesis and obesity." (PMID 35126382, 2021).
breast carcinoma (2 papers, 2021). "A Kaplan-Meier analysis revealed that lower expression of Arid5a mRNA was associated with poor overall survival in the luminal type and all breast cancer patients." (PMID 35126382, 2021). "In addition, Arid5a deficiency in 4T1 cells decreased the invasion and metastasis of breast cancer cells in in vitro and in vivo studies." (PMID 35126382, 2021). "Based on an analysis of online datasets, Arid5a is considered a good candidate for tumor treatment in breast cancer; however, it will be necessity to conduct further studies to provide more experimental evidence." (PMID 35126382, 2021). "K-M plotter analysis showed that low mRNA expression of ARID5A was obviously related with poor OS in luminal type and all breast cancer patients." (PMID 33592583, 2021). "A database mining study recently assessed the expression of Arid family members including Arid5a based on The Cancer Genome Atlas (TCGA) data and also evaluated the prognostic value of each member in breast cancer patients." (PMID 35126382, 2021). "Combining our results, we speculated ARID5A would be a good candidate gene as a tumor suppressor in breast cancer." (PMID 33592583, 2021). "This study may lead to strategies for using Arid5a and lncRNA for the treatment of breast cancer." (PMID 35126382, 2021). "Low mRNA expression of ARID1A (p=0.0096), ARID2 (p=0.0066), ARID3B (p= 0.000024), ARID5A (p=0.0435), ARID5B (p=0.0022), JARID1A (p=0.0044), JARID2 (p=0.0463) were interrelated with worse OS in grade III breast cancer patients." (PMID 33592583, 2021). "Conversely, Arid3c, Arid5a, and Jarid2 mRNA expression was higher in non-luminal subtypes of breast cancer." (PMID 35126382, 2021). "Arid5a under IL6 signaling binds to the upstream region of a lncRNA, AU021063, and transcriptionally upregulates the expression of this noncoding RNA, which further leads to the enhanced invasion and metastasis of breast cancer cells in mice by stabilizing the tribbles homolog 3 (Trib3) protein." (PMID 35126382, 2021). "The expression of ARID1A, ARID1B, ARID2, ARID3A, ARID4A, and ARID4B in no-luminal subtypes was lower than luminal subtypes, however, ARID3C, ARID5A, and JARID2 mRNA expression were higher in no-luminal subtypes of breast cancer tissues." (PMID 33592583, 2021).
mesenchymal tumors (2 papers, 2021 to 2022). "However, the molecular mechanisms underlying the regulation of Arid5a in mesenchymal tumors remain unclear and these mechanisms will be interest in future studies, especially in targeting Arid5a for tumor immunotherapy." (PMID 35126382, 2021). "Recently, the expression levels of Arid5a have been reported to be significantly increased in mesenchymal tumor subtypes of PDAC and CRC, such as the quasi-mesenchymal and consensus molecular subtype 4 subtypes, respectively." (PMID 36010693, 2022). "It has been shown that Arid5a enables mesenchymal tumor models of PDAC and CRC to facilitate immune evasiveness via promoting the tumor infiltration of immunosuppressive granulocytic MDSCs and Tregs and reducing the recruitment and activation of antitumor effector T cells." (PMID 36010693, 2022).
Arthritis (1 paper, 2026). Inflammation of a joint. "Arid5a-/- mice were resistant to collagen-induced arthritis correlating with reduced Th17 cells in synovial tissue." (PMID 41574607, 2026).
B cell lymphoma (1 paper, 2022). "In mouse CD1d– ATA B cell lymphoma, we observed reduced LEF-1 and increased IL-6 and Arid5a." (PMID 36050343, 2022). "The strong ATA B cell lymphoma stages in mice were CD1d–, LEF-1–, and IL-6+ with increased Arid5a." (PMID 36050343, 2022).
bipolar disorder (1 paper, 2024). A disorder of the brain that causes unusual shifts in mood, energy, activity levels and the ability to carry out day-to-day tasks. "ARID5A, a gene implicated in the most recent TWAS on PGC bipolar disorder, is one example of these genes." (PMID 38306997, 2024). "In the bulk expression, the TWAS Z score of ARID5A and bipolar disorder is −4.99 (TWAS Z score −5.32 in PGC BP study), whereas in CD8 T cells it is +6.02." (PMID 38306997, 2024).
colitis (1 paper, 2025). Inflammation of the colon. "For instance, TEAD1 is a component of the Hippo pathway that has been found to exert immunomodulatory effects in murine models of colitis, and ARID5A, regulates the expression of genes downstream of the Th17/IL-17 axis, a pathway known to play a critical role in IBD pathogenesis." (PMID 40914875, 2025).
colorectal cancer (1 paper, 2023). A primary or metastatic malignant neoplasm that affects the colon or rectum. "Recent studies highlighted the regulatory role of ARID5A in various cancers, including lung, breast, prostate, PDAC, and colorectal cancer." (PMID 37605192, 2023).
heart failure (1 paper, 2020). Inability of the heart to pump blood at an adequate rate to meet tissue metabolic requirements. "Arid5a could be a therapeutic target for cardiac inflammation in heart failure." (PMID 32302067, 2020).
lymphoma (1 paper, 2022). A malignant (clonal) proliferation of B- lymphocytes or T- lymphocytes which involves the lymph nodes, bone marrow and/or extranodal sites. "Thus, we propose that Arid5a-IL-6 interactions in CD1d– (IL-5R–) B1 B cells may have promoted the development of lymphoma, different from NKT2 connecting CD1d+B1 B cells." (PMID 36050343, 2022).
metastatic cancers (1 paper, 2021). A carcinoma which has spread from the original site of growth to another anatomic site. "We also identified six genes (KHDRBS2, IQSEC1, ARHGEF1, ARID5A, IRX5, and TMC6) that were activated in metastatic cancers in two of the three cancer types and might be associated with metastatic traits." (PMID 34294701, 2021).
neuroblastoma (1 paper, 2013). Neuroblastoma (NB) is the most common solid, extracranial childhood tumor. "Interestingly ARID5A was among these 30 de novo mutant genes unique to Met2, and a recent sequencing study has reported that mutations in the chromatin-remodeling genes ARID1A and ARID1B in neuroblastoma were associated with a more aggressive phenotype." (PMID 24147068, 2013).
prostate carcinoma (1 paper, 2021). A carcinoma that arises from epithelial cells of the prostate gland. "Whereas the Il6 gene is transcriptionally upregulated by Arid5a in prostate cancer cells, Arid5a increases the half-life of Il6 mRNA at the post-transcriptional level in immune cells, such as macrophages, which further suggests a cell-specific function of Arid5a." (PMID 35126382, 2021).
tumor (13 papers, 2020 to 2024). "However, the underlying mechanism by which ARID5A influences TILs in the tumor immune microenvironment needs further study." (PMID 34094918, 2021). "Another study reported high expression of Arid5a expression is associated with complex tumor malignancy, suggesting that Arid5a may be a useful marker for the degree of tumor malignancy." (PMID 35126382, 2021). "Thus, the molecular mechanisms underlying the regulation of ARID5A in tumor could be of interest in future studies." (PMID 37605192, 2023). "In a tumor model, ARID5A, an RNA-binding protein, acts as an mRNA stabilizer to promote IDO1 expression." (PMID 39438693, 2024). "Arid5a is involved in immune evasion by promoting tumour invasion through gMDSCs and Tregs and inhibiting the recruitment and activation of antitumour effector T cells." (PMID 38783078, 2024). "From the findings above, we can conclude that the increased expression of ARID5A was related to an increase in tumor malignancy." (PMID 34094918, 2021). "An association of Arid5a-regulated molecules, such as IL6, Tbet, Stat3, Ox40, and Pparγ, has been widely studied in various cancers and tumor models." (PMID 35126382, 2021). "This prompted us to consider the possibility of an Arid5a-mediated immunosuppressive effect in the tumor microenvironment (TME)." (PMID 35126382, 2021). "We found that the expression of ARID5A was significantly upregulated with an increase in tumor malignancy." (PMID 34094918, 2021). "Arid5a−/− tumor cells produced smaller tumors in immunocompetent mice compared with immunodeficient mice, which further supports a role for Arid5a in immune evasion and immunosuppression in the TME." (PMID 35126382, 2021). "The mRNA expression of Arid3a, Arid3b, Arid4b, Jarid1b, Jarid1c, and Jarid2 was higher, whereas Arid1b, Arid3c, Arid4a, Arid5a, Arid5b, and Jarid1a mRNA expression was lower in tumor tissues compared with controls." (PMID 35126382, 2021). "We found that ARID5A expression in tumor tissues was significantly higher than that in normal tissues (P <0.001)." (PMID 34094918, 2021). "We found that the injection of Arid5a−/− tumor cells into immunocompetent and immunodeficient mice resulted in smaller tumors in the immunocompetent mice compared with the immunodeficient mice." (PMID 35126382, 2021). "Furthermore, gene expression analysis based on chip datasets in GEO demonstrated that ARID5A was significantly highly expressed in tumor tissues (paired or unpaired samples)." (PMID 37605192, 2023). "Protein expression analysis also revealed significantly higher levels of ARID5A in tumor tissues." (PMID 37605192, 2023). "Collectively, these findings indicated that ARID5A may be involved in the formation of tumor microenvironment through the interferon-gamma-mediated signaling pathway." (PMID 34094918, 2021). "In our study, expression of ARID3C and ARID5A were lower in tumor tissues than in normal tissues." (PMID 33592583, 2021). "Therefore, high expression of ARID5A in tumor tissue may serve as a potential target for PDAC immunotherapy." (PMID 37605192, 2023). "Moreover, Arid5a expression was associated with the mesenchymal phenotypes of CRC and PDAC, and Arid5a is involved in immune evasion by promoting tumor infiltration by MDSCs and Tregs, and by suppressing the recruitment and activation of antitumor effector T cells." (PMID 35126382, 2021). "Pan-cancer expression analysis revealed that ARID5A was significantly overexpressed in tumor tissues of GBM, KIRC, LAML, and PAAD, while it showed lower expression in tumor tissues of BLCA, BRCA, and CESC." (PMID 37605192, 2023). "Like ARID5A, mRNA expression of ARID5B was interrelated with better survival in our study, which indicated the function of a tumor suppressor." (PMID 33592583, 2021).
tumor (continued). "The mRNA expression of ARID3A, ARID3B, ARID4B, JARID1B, JARID1C, JARID2 in tumor tissues was more expressive in normal tissues, ARID1B, ARID3C, ARID4A, ARID5A, ARID5B, JARID1A mRNA expression in tumor tissues were lower than that in the normal tissues (p<0.05)." (PMID 33592583, 2021). "Conversely, a negative correlation between ARID5A/ARID5B and tumor purity was found." (PMID 36034939, 2022).
cancer (7 papers, 2020 to 2023). A tumor composed of atypical neoplastic, often pleomorphic cells that invade other tissues. "Arid5a regulates the quiescence stage by increasing the G0/G1 phase in human cancer cells; thus, it is regarded as a quiescence-associated marker." (PMID 33261017, 2020). "However, an in-depth understanding of Arid5a in the biological processes of cancer and associated TME requires further study." (PMID 35126382, 2021). "The analysis of ARID5A expression in pan-cancers and immunohistochemical results indicate its high expression in PDAC." (PMID 37605192, 2023). "Mechanistically, Arid5a functions as a dual regulator, leading to the formation of immunosuppressive TMEs in malignant tumors and triggering the metabolic reprograming and recruitment of suppressive immune cells." (PMID 36010693, 2022). "Recent studies have demonstrated the crucial roles of Arid5a in inflammation, autoimmunity, and cancer." (PMID 36010693, 2022). "Nonetheless, Arid5a controls several biological processes in cancer such as invasion, metastasis, reprogramming M2-like TAMs to M1-like TAMs, immune suppression/immune evasion in the TME, and regulation of lncRNAs." (PMID 35126382, 2021). "Finally, in-depth research of the expression and function of Arid5a not only in immune-related diseases but also in cancers can provide accurate diagnostic values and reliable prognostic pieces of evidence, and may thus improve the clinical therapeutics of these diseases." (PMID 35126382, 2021). "By discussing potential mechanisms of Arid5a and its influential roles in immunological disorders and cancer, we aim to encourage discussion on recent advances in Arid5a research." (PMID 35126382, 2021). "In contrast we demonstrated a role for Arid5a in immune evasion by augmenting tryptophan metabolism and chemokine expression in cancer." (PMID 35126382, 2021). "Interestingly, pan-cancer analysis revealed different prognostic implications of ARID5A in distinct cancer subtypes within the same organ." (PMID 37605192, 2023). "This suggests that Arid5a represents a therapeutic target in cancer." (PMID 35126382, 2021). "An in-depth understanding of the role of Arid5a in these cancer models will contribute to the development of prognostic and response biomarkers and may lead to new therapeutic strategies." (PMID 35126382, 2021). "Therefore, it is likely that Arid5a contributes to many processes in cancer cells." (PMID 35126382, 2021). "Concerning ARID3C and ARID5A, there were no studies carried on the relationship between them and cancers as yet." (PMID 33592583, 2021). "Arid5a, which functions as a TF and RBP, was recently shown to be involved in cancer." (PMID 35126382, 2021).
inflammation (3 papers, 2020 to 2022). Aberrant reaction of the microcirculation characterized by movement of fluid and leukocytes from the blood into extravascular tissues. "β2AR/Arid5a/IL‐6 axis could be a therapeutic target against cardiac inflammation." (PMID 32302067, 2020).
infection (2 papers, 2022 to 2025). The state of being infected such as from the introduction of a foreign agent such as serum, vaccine, antigenic substance or organism. "In contrast, infection led to an upregulation of the pro-tumorigenic gene Arid5a, with the highest expression observed in the SFV/IFNγ group." (PMID 40547518, 2025). "Similar to the findings of IL-6, the expression of arid5a was also significantly increased at 6 h after infection." (PMID 36059498, 2022).
ARID5A also shares sentences with these, for which no sentence is quoted: Sepsis (2 papers); acute myeloid leukemia (1); acute pancreatitis (1); Alzheimer disease (1); Immune Diseases (1); non-small cell lung carcinoma (1).